OXTR (oxytocin receptor)
Diseases named in the same sentence as OXTR in open-access papers (continued):
Sharing a sentence is not in itself a finding about the gene and the disease.
schizophrenia (continued). "OXT and AVPR1a gene expression was significantly lower in the schizophrenia group than in the controls, whereas OXTR and AVP gene was significantly higher in the schizophrenia subjects than in the controls." (PMID 35723404, 2022). "In a postmortem study, downregulation of oxytocin receptor mRNA in the temporal cortex was found in patients with schizophrenia." (PMID 33670047, 2021). "So, in this study, we determined the relative mRNA expression of OXT and OXTR genes in first-episode, unmedicated schizophrenia (FES) patients and HC." (PMID 31024366, 2019). "MANCOVA of 3 IRI scores in schizophrenia patients (SZ, n = 145) and healthy controls (HC, n = 145); factors: OXTR rs2254298 (GG vs. A carriers), OXTR rs53576 (GG vs. A carriers) and diagnosis, covariate: verbal IQ." (PMID 23284802, 2012). "Raw data of IRI scores (mean, SD) by OXTR rs2254298 and rs53576 genotypes in schizophrenia patients (SZ, n = 145) and healthy controls (HC, n = 145)." (PMID 23284802, 2012). "OXTR SNPs that were previously investigated in other studies were genotyped in 145 patients diagnosed with schizophrenia according to DSM-IV and 145 healthy controls matched for age and gender." (PMID 23284802, 2012). "Future studies could incorporate more covariates, such as medication history, allowing for a more comprehensive analysis of the relationships between the OXTR gene and schizophrenia." (PMID 38184684, 2024). "It was reported that OXTR and GHSR can form heterocomplexes, leading to significant changes in downstream OXTR signaling, which may also be relevant to the mechanism through which ghrelin affects schizophrenia." (PMID 40226675, 2024). "Given the exploratory nature of this study, these associations are indicative of the role of the OXTR gene in the pathology of schizophrenia though they did not remain significant after multiple testing correction." (PMID 38184684, 2024). "Furthermore, compared with healthy controls, schizophrenia patients showed downregulated expression of OXTR in the temporal cortex and decreased receptor binding in the vermis." (PMID 37153633, 2023). "Studies report a significant association between negative symptom scores as measured by the PANSS scale (positive and negative schizophrenia symptoms scale) and oxytocin receptor variants rs53576 and rs237885." (PMID 35888641, 2022). "Single Nucleotide Polymorphisms (SNPs) of the OXTR gene have been associated with alterations in sociality and emotional responsiveness in humans and several SNPs could be linked to ASD and schizophrenia." (PMID 35688807, 2022). "Moreover, the expression of OXT, OXTR, and AVPR1a genes both at the mRNA and protein levels differed statistically significantly in the group of individuals that were suffering from schizophrenia for a long and short period." (PMID 35723404, 2022). "The oxytocin gene and oxytocin receptor gene are important for the regulation of the oxytocinergic system and may contribute to the pathophysiology of schizophrenia." (PMID 33670047, 2021). "The impact of OXTR polymorphisms on prosocial attitudes in schizophrenia extends reports of an influence of peripheral OXT levels on prosocial symptom scores, emotion recognition, social cognition and trust in schizophrenia." (PMID 23284802, 2012). "Therefore, the expression of the OXTR gene may be different in the brains and in the peripheral tissues of schizophrenia patients; however, dysregulation of this gene in this disease is evident." (PMID 36835321, 2023). "Additionally, although not fully proven in schizophrenia, oxytocin receptor gene polymorphism, including rs53576 and rs2254298, was found to play an important role in glucose homeostasis." (PMID 35806096, 2022). "Furthermore, the oxytocin receptor (OXTR) have been shown to interact with the ghrelin receptor (GHSR), suggesting that ghrelin-targeted therapy may be able to control oxytocin signaling associated with schizophrenia." (PMID 40226675, 2024).
schizophrenia (continued). "The expression of OXT, OXTR, AVP, and AVPR1a genes at the mRNA and protein levels differ between the studied groups of patients with schizophrenia and the control group." (PMID 35723404, 2022). "The aim of this study was to evaluate the expression of OXT, OXTR, AVP, and AVPR1a genes at the mRNA and protein levels in patients with schizophrenia." (PMID 35723404, 2022). "The aim of this study was to evaluate the expression of OXT, OXTR, AVP, and AVPR1a genes at the mRNA and protein levels in patients who have been suffering from schizophrenia for a long or short time." (PMID 35723404, 2022). "Early modulation of OXTR levels is of particular importance when considering neurodevelopmental disorders, many of which are characterized by deficits in social abilities and social cognition e.g. autism spectrum disorders (ASD) and schizophrenia." (PMID 36998737, 2023). "The statistical analyses comparing the expression values of OXT, OXTR, AVP, and AVPR1a genes in the investigated groups allow us to conclude that all the examined genes may participate in the etiopathogenesis of schizophrenia." (PMID 35723404, 2022). "However, genetic data on PRLRH, PRLR, OXT, OXTR, and NPY in human T2DM and schizophrenia patients are scarce." (PMID 33315097, 2021). "Other candidate genes, PRL-releasing hormone receptor (PRLRH), PRL receptor (PRLR), oxytocin (OXT), oxytocin receptor (OXTR), and NPY, may also correlate with the PRL pathway and contribute to schizophrenia and T2DM." (PMID 33315097, 2021). "In this study, serum OXT, OXT receptor (OXTR), interleukin-6 (IL-6), high sensitivity CRP (hsCRP) and homocysteine (Hcy) levels were measured in 52 first-episode schizophrenia (FES) patients and 41 healthy controls (HC) from the Second Xiangya Hospital of Central South University." (PMID 31024366, 2019). "Within the schizophrenia group, linear regression analysis determined OXTR rs2254298 genotype, PANSS negative and general symptom score, and age of disease onset as being significantly associated with ‘empathic concern’." (PMID 23284802, 2012). "Using the same questionnaire, our result substantiates a possible influence of OXTR rs2254298(A>GG), but not OXTR rs53576, on emotional empathy also in schizophrenia." (PMID 23284802, 2012). "Linear regression analysis identified not gender, but OXTR rs2254298(A), late age of onset of schizophrenia, low PANSS negative, and high PANSS general psychopathology scores as predictors of high self-rated ‘empathic concern’." (PMID 23284802, 2012). "OXT, OXTR, AVP, and AVPR1a are genes that may be involved in the development of schizophrenia." (PMID 35723404, 2022). "Although mediation analysis in our sample did not confirm significant indirect effects, OXTR rs2254298 A-carriers might represent the more “affective” pole of our schizophrenia sample, with PANSS general scores reflecting the predominance of affective, anxious and psychomotor symptoms." (PMID 23284802, 2012).
breast carcinoma (22 papers, 2007 to 2026). "The oxytocin receptor (OTR) is a class-A G protein-coupled receptor that has been linked to breast cancer, but its role in tumorigenesis and disease progression remains underexplored." (PMID 35884900, 2022). "The OXTR-oxytocin axis has been implicated in preventing the emergence of breast cancer." (PMID 34877409, 2021). "This investigation was carried out to assess OT variation in breast carcinoma patients and OXTR expression alterations in breast cancer tissues." (PMID 37900385, 2023). "Some studies also noticed that OXTR is present in the nucleus of human osteosarcoma and breast cancer cell lines." (PMID 38001957, 2023). "A reduced expression of OXTR in malignant tissues appears to be helpful in the evolution of breast cancer despite the elevated levels of OT concentration in breast cancer patients." (PMID 37900385, 2023). "OT concentration and OT receptor (OXTR) expression changes have varying impacts on cells originating from breast cancer." (PMID 37900385, 2023). "Similar to 5-HTT and NR3C1, the expression of OXTR is also related to the clinical outcomes of breast cancer." (PMID 36430579, 2022). "The molecular analysis of the isolated epithelial cells showed RGS2 overexpression in breast cancer cells and the modulation of the signal transduced by the oxytocin receptor for the protein." (PMID 35453754, 2022). "We profiled the expression of selected stress-associated genes (5-HTT, NR3C1, OXTR, and FKBP5) in breast cancer including the stress evaluation of all participants using the Questionnaire on Distress in Cancer Patients–short form (QSC-R10)." (PMID 36430579, 2022). "The role of OXTR in tumorigenesis should be assessed extensively in breast cancer to identify its concrete role in all breast cancer subtypes." (PMID 36430579, 2022). "Several previous studies have demonstrated that the activation of OXTR-mediated signaling promotes or prevents tumorigenesis and metastasis in multiple cancers, including breast cancer, non-small-cell lung cancer, prostate cancer, and ovarian cancer." (PMID 34877409, 2021). "OXTR has been found highly expressed in pathological breast, breast carcinomas, neuroblastomas, and astrocytomas." (PMID 34099636, 2021). "OXTR-induced hyperprolactinemia, unexpected milk production (nipple discharge), and mammary hyperplasia are all early characteristics of human breast cancer." (PMID 34099636, 2021). "In conclusion, we have found OXTR overexpression induces ERBB2+ mammary tumors through activation of PRL/p-STAT5 pathway." (PMID 34099636, 2021). "OXTR induces hormonal changes and creates a mammary gland-specific environment that promotes mammary tumor growth." (PMID 34099636, 2021). "OXTR-induced mammary tumors showed ERBB2 upregulation and mixed histological subtypes with predomination of papillary and medullary carcinomas." (PMID 34099636, 2021). "OXTR, oxytocine receptor gene (80-fold) has also been detected in breast cancer cells with intrinsic and acquired resistance to doxorubicin." (PMID 22905093, 2012). "The peptide hormone oxytocin receptor (OTR)is one such emerging target in breast cancer." (PMID 38235665, 2024). "Hence, the oxytocin receptor genotype holds promise as a predictor of resilience in breast cancer patients." (PMID 37781188, 2023). "Although oxytocin receptor signaling may stimulate some aspects of breast cancer progression in vitro, oxytocin’s net impact in vivo seems to inhibit cancer, hinting at complex context-dependent effects." (PMID 37781188, 2023). "Moreover, OXTR has been proposed to play a role in breast cancer development and progression, though mechanism(s) of this connection remain(s) to be elucidated." (PMID 36835321, 2023). "OXTR expression was detected in human breast cancer cells T47D, MCF7, ZR-75-30, and MDA-MB-231." (PMID 34099636, 2021). "OXTR overexpression may have created a microenvironment that specifically promotes mammary tumor growth." (PMID 34099636, 2021).
breast carcinoma (continued). "Gene expression pattern supports that OXTR overexpression induces ERBB2+ mammary tumors." (PMID 34099636, 2021). "The study suggested that high oxytocin receptor levels are associated with increased EGF sensitivity and that oxytocin receptors promote EGF-stimulated RSK activation via the mTOR pathway, leading to downstream rpS6 activation and enhanced migration of breast cancer cells." (PMID 37781188, 2023). "However, after intraperitoneal oxytocin administration to mammary carcinoma mice (MC4-L2), the mRNA expression of miR-195 and its associated signaling pathways, such as dephosphorylated Akt and ERK, the oxytocin receptor, and Bax genes, was significantly increased." (PMID 37781188, 2023). "Thus, in breast cancer patients, changes in plasma oxytocin levels and peripheral oxytocin receptor distribution may influence psychological resilience and the ability to mentally cope with a crisis or quickly return to pre-crisis status." (PMID 37781188, 2023). "In addition, Br is an effective antitumor drug for OXTR/PRL-driven HER2+ breast cancer." (PMID 34099636, 2021). "PRL inhibitor bromocriptine (Br) could mitigate OXTR-driven mammary tumor growth." (PMID 34099636, 2021). "The relationship of OXTR, hyperprolactinemia, and ERBB2 expression in breast cancer is established in this study." (PMID 34099636, 2021). "Oxytocin receptor (OXTR) is involved in social behaviors, thermoregulation, and milk ejection, yet little is known about its role in breast cancer." (PMID 34099636, 2021). "On the other hand, the down-regulation of the OXTR gene expression was reported recently in breast cancer relative to the non-cancer tissue." (PMID 36835321, 2023). "To confirm differential gene expression levels in the three breast cancer subtypes, Her2+, ER + and TNBC, we selected 6 genes (ITGA3, ITGA5, OXTR, WNT5B, BCAR1, FZD1) with significantly different levels of expression based on our microarray studies and validated their expression levels by qRT-PCR." (PMID 22954256, 2012). "The RGS2 gene, but not the oxytocin receptor, was also shown to be over-expressed in the majority of breast cancers, identifying the product of this gene, or the pathway(s) it regulates, as potentially significant therapeutic targets." (PMID 18067675, 2007). "The RGS2 gene, but not the OXTR gene, was also shown to be over-expressed in the majority of breast cancers, identifying the product of this gene, or the pathway(s) it regulates, as potentially significant therapeutic targets." (PMID 18067675, 2007). "RGS2 and OXTR expression levels were not correlated in breast cancer, suggesting that RGS2 modulates a different GPCR pathway(s) in breast tumours." (PMID 18067675, 2007). "However, because the function of RGS2 is unlikely to be mediated through oxytocin receptor signalling in breast cancer, its role in the pathogenesis of the disease remains to be elucidated." (PMID 18067675, 2007). "Expression levels of OXTR, FOS, ITPR1, RCAN1, CAMK2D, CACNA2D and lnc_ZFP161 were significantly down-regulated in the breast cancer tissues compared with nearby non-cancerous tissues." (PMID 33742056, 2021). "We identified down-regulation of OXTR, FOS, ITPR1, RCAN1, CAMK2D, CACNA2D and lnc_ZFP161, and up-regulation of lnc_MTX2 in the breast cancer tissues compared with nearby non-cancerous tissues." (PMID 33742056, 2021). "Expression levels of OXTR, FOS, ITPR1, RCAN1, CAMK2D, CACNA2D and lnc_ZFP161 were significantly down-regulated in breast cancer tissues compared with nearby non-cancerous tissues." (PMID 33742056, 2021). "Notably, multiple sex-biased switch-like genes—including SPINT1 and SPINT234, multiple keratin genes 35, and the oxytocin receptor gene 36,37 (OXTR)—in the breast tissue are differentially expressed in breast cancers relative to matched non-cancerous tissues." (PMID 39315271, 2024).
anxiety disorder (16 papers, 2012 to 2025). A category of psychiatric disorders which are characterized by anxious feelings or fear often accompanied by physical symptoms associated with anxiety. "Studies also suggest that oxytocin and OXTR play a role in psychiatric disorders, such as anxiety disorders and autism." (PMID 30655508, 2019). "Two studies examining OXTR DNAm in the exon 3 region from blood and anxiety disorders were identified." (PMID 29843655, 2018). "In our sample, state anxiety derived from the STAI questionnaire was neither associated with OXTR methylation rates nor salivary OXT measurements, neither in HC nor in FND patients." (PMID 39726815, 2025). "We propose that the decrease in OXTR mRNA transcription after long-term isolation may induce depressive and anxiety disorders by reducing GABA release and consequently, disinhibiting CeA neurons." (PMID 30158853, 2018). "Anxiety disorders have previously been linked to differential methylation of specific genes (MAOA, CRHR1, OXTR), and functional magnetic resonance imaging has revealed that the temporal and prefrontal regions of the brain respond differently in patients with anxiety disorders." (PMID 36846567, 2023). "With regard to anxiety disorders (including generalized anxiety disorder, panic disorder and phobias), only a few GWAS and candidate gene studies have been reported in clinical samples so far, with no report of any direct associations with the OXTR gene." (PMID 28353027, 2017). "Despite these considerable limitations, emerging evidence points to increased OXTR DNAm in general impairments of social, cognitive and emotional functioning, and decreased OXTR DNAm in specific patterns of impairment related to mood and anxiety disorders (but not in all)." (PMID 29843655, 2018). "However, taken together, findings point to increased OXTR DNAm in general impairments in social, cognitive and emotional functioning, and decreased OXTR DNAm in specific patterns of impairment related to mood and anxiety disorders (but not in all)." (PMID 29843655, 2018).